CPA4 (carboxypeptidase A4)
Diseases named in the same sentence as CPA4 in open-access papers (continued):
Sharing a sentence is not in itself a finding about the gene and the disease.
tumor (continued). "Data analysis showed that the expression of SRM and CPA4 mRNAs in tumor tissue increased compared to the adjacent normal tissue, while the expression of SOX4 mRNA did not change." (PMID 39028420, 2024). "On the contrary, CM-272 increased levels of genes related to tumor growth suppression: CPA4 (Carboxypeptidase A4), a negative regulator of the AKT/c-MYC pathway in NSCLC and GNG2 (G-protein gamma subunit 2), which impairs AKT phosphorylation and cell survival." (PMID 39488528, 2024). "However, after CPA4 was stably silenced in HLCZ01-ETR1R, subcutaneous tumours were implanted in NCG mice, and when the tumour volume was approximately 100 m3, subcutaneous injection of HGS-ETR1 was performed to kill the tumour." (PMID 38049405, 2023). "Subcutaneous tumour transplantation was performed in NCG mice, and the results showed that overexpression of CPA4 in HLZ01 cells could resist the tumour-killing effect of HGS-ETR1/2." (PMID 38049405, 2023). "Then, we performed qRT‐PCR to evaluate CPA4 gene expression in 20 tumor tissues and corresponding nontumor tissues." (PMID 31397502, 2019). "Since CPA4 presented the opposite relationship to Treg and Th17 cells, this could have negative implications for the treatment of aggressive tumours." (PMID 38494845, 2024). "There are also a few reports that CPA4 can inhibit the apoptosis process of tumour cells through the AKT signalling pathway, but no studies have explored how CPA4 regulates the phosphorylation process of AKT, and no studies on its relationship with pyroptosis have been reported." (PMID 38049405, 2023).
infection (1 paper, 2023). The state of being infected such as from the introduction of a foreign agent such as serum, vaccine, antigenic substance or organism. "Overexpression of CPA4 in HLCZ01 cells via a lentiviral infection system was found to inhibit HGS-ETR1/2-induced GSDME cleavage, and the number of pyroptotic cells decreased, LDH release and the number of PI-positive cells decreased." (PMID 38049405, 2023).
CPA4 also shares sentences with these, for which no sentence is quoted: asthma (1 paper); autism (1); clear cell renal cell carcinoma (1); Obesity (1); osteosarcoma (1); ovarian carcinoma (1); rectal cancer (1); Silver Russel syndrome (1).